RNU6-1051P (RNA, U6 small nuclear 1051, pseudogene)
Gene: Small nuclear RNA gene on chromosome 2 (237,015,204 to 237,015,305, reverse strand). Ensembl gene ENSG00000202341.
Homologues: Orthologues: chimpanzee U6 (100% identical), macaque U6 (94% identical), pig U6 (71% identical). Paralogues in human: RNU6-38P (87% identical), RNU6-1145P (86% identical), RNU6-639P (86% identical), RNU6-1011P (85% identical), RNU6-20P (85% identical), RNU6-468P (85% identical), RNU6-476P (85% identical), RNU6-15P (84% identical), RNU6-214P (84% identical), RNU6-29P (84% identical), RNU6-345P (84% identical), RNU6-574P (84% identical), and 1285 more.